MTSS2 (MTSS I-BAR domain containing 2)
Description:
Involved in plasma membrane dynamics. Potentiated PDGF-mediated formation of membrane ruffles and lamellipodia in fibroblasts, acting via RAC1 activation. May function in actin bundling.
Synonyms: ABBA-1; MTSS1L; LOC92154; ABBA; ABBA1; IDDOF
Tractability: Antibody: its Gene Ontology location is reachable by antibodies, with medium confidence. PROTAC: ubiquitination databases record sites on it.
Gene: Protein-coding gene on chromosome 16 (70,661,204 to 70,686,053, reverse strand). Ensembl gene ENSG00000132613.
Subcellular location: Cytoplasm; Cell projection, ruffle
Subcellular location (Human Protein Atlas): Focal adhesion sites
Gene Ontology:
Molecular function: GTPase activator activity; protein binding; small GTPase binding; actin binding; phospholipid binding; actin monomer binding; phosphatidylinositol-4,5-bisphosphate binding
Biological process: activation of GTPase activity; cellular response to platelet-derived growth factor stimulus; membrane organization; plasma membrane organization
Cellular component: cytoplasm; focal adhesion; ruffle membrane; actin cytoskeleton; cortical actin cytoskeleton; lamellipodium; plasma membrane; ruffle
Genetic constraint (gnomAD): Loss-of-function variants: 27 observed, 56.26 expected, observed/expected ratio (o/e) 0.48, 90% interval 0.35 to 0.66. The synonymous counts are far from expectation, so gnomAD's model fits this gene poorly and the ratio says little. Missense variants: 1,171 observed, 949.56 expected, observed/expected ratio (o/e) 1.23, 90% interval 1.17 to 1.29. Synonymous variants: 624 observed, 419.47 expected, observed/expected ratio (o/e) 1.49, 90% interval 1.39 to 1.59.
Homologues: Orthologues: chimpanzee MTSS2 (99% identical), rat Mtss2 (97% identical), pig MTSS2 (94% identical), dog MTSS2 (94% identical), rabbit MTSS2 (92% identical), mouse Mtss2 (91% identical), macaque MTSS2 (88% identical), guinea pig MTSS2 (77% identical), tropical clawed frog mtss2 (77% identical), zebrafish mtss1lb (76% identical), zebrafish mtss1la (67% identical), Caenorhabditis elegans M04F3.5 (22% identical). Paralogues in human: MTSS1 (58% identical).
Diseases named in the same sentence as MTSS2 in open-access papers:
MTSS2 is named in the same sentence as 15 diseases in open-access papers, as found by Europe PMC text mining. Sharing a sentence is not in itself a finding about the gene and the disease. The quoted sentences say what the papers report.
Intellectual disability (2 papers, 2025). "Notably, we identified a variant of Mtss2 (R671W) in a patient with microcephaly and intellectual disability, further highlighting its significance." (PMID 40698928, 2025). "Importantly, these results are in accord with the reported association of MTSS2 with developmental neurological diseases, including intellectual disability and microcephaly." (PMID 40698928, 2025). "Patients with the MTSS2 Arg671Trp mutation exhibit a spectrum of neurodevelopmental symptoms, including global developmental delay, mild intellectual disability, ophthalmological anomalies, microcephaly or relative microcephaly, autism, and distinct facial features." (PMID 41359239, 2025). "Based on our results, we reason that defective spine initiation can play a role in MTSS2-linked syndromic intellectual disability, but this might not be the only cause for observed symptoms, because ABBA appears to be a multifunctional protein." (PMID 41359239, 2025).
microcephaly (2 papers, 2025). A congenital or acquired developmental disorder in which the circumference of the head is smaller than normal for the person's age and sex. "In this scenario, heterozygous expression of the human R671W variant would exert a dominant negative effect on MTSS2’s role in brain development, leading to microcephaly and cognitive delay." (PMID 40698928, 2025). "Overall, these findings offer valuable mechanistic insights into the development of microcephaly and the cerebral cortex by identifying Mtss2 as a novel regulator involved in ensuring the accurate progression of mitosis in neuronal progenitor cells." (PMID 40698928, 2025).
brain malformation (1 paper, 2025). "Moreover, recent publications found six additional patients carrying the same MTSS2 variant that shared similar brain malformation." (PMID 40698928, 2025).
glioma (1 paper, 2025). A benign or malignant brain and spinal cord tumor that arises from glial cells (astrocytes, oligodendrocytes, ependymal cells). "Revalidation of the knockdown efficiency of this target with three different Mtss2-shRNA (Mtss2-shRNA1-3) in rat C6 glioma cells showed a 70–80% reduction of Mtss2 mRNA and protein levels with Mtss2-shRNA3." (PMID 40698928, 2025). "To further characterize the role of Mtss2 in mitotic progression, we synchronized C6 rat glioma cell line and stained with Mtss2 antibody." (PMID 40698928, 2025).
intellectual disability syndrome (1 paper, 2025). "A missense mutation in the MTSS2 gene, which encodes the I-BAR domain protein ABBA (Mtss1l/Mtss2), has been linked to an intellectual disability syndrome." (PMID 41359239, 2025).
leukemia (1 paper, 2025). A malignant (clonal) hematologic disorder, involving hematopoietic stem cells and characterized by the presence of primitive or atypical myeloid or lymphoid cells in the bone marrow and the blood. "Besides lymphoma- and/or leukemia-related genes, the most frequently mutated tumor suppressor genes included AFAP1L1, FBN3, MTSS2, and TTLL5, with each being mutated in at least 10% of cHL cases." (PMID 41296384, 2025).
lymphoma (1 paper, 2025). A malignant (clonal) proliferation of B- lymphocytes or T- lymphocytes which involves the lymph nodes, bone marrow and/or extranodal sites. "WES revealed significantly mutated genes, including several known (NCF1, MMP9, and VDR) and possibly other candidate (CNN2, MUC4, MTSS2, KMT2C, HAVCR2, and TCF19) genes, most of which were associated with the physiological activation of lymphoma cells." (PMID 41296384, 2025).
cancer (7 papers, 2008 to 2024). A tumor composed of atypical neoplastic, often pleomorphic cells that invade other tissues. "A few candidate genes, such as ZBTB21, MTSS2, and EBF4, still have elusive functional mechanisms, while belonging to families of genes with suggested roles in cancer susceptibility." (PMID 34067022, 2021).
tumor (2 papers, 2024 to 2025). "Similarly, PSMB5 and MTSS2 were expressed higher in the snRNA-Seq tumour cells." (PMID 41168392, 2025).
MTSS2 also shares sentences with these, for which no sentence is quoted: breast carcinoma (2 papers); bipolar disorder (1); cognitive delay (1); Gliosis (1); melanoma (1); neuroblastoma (1).